GJD3-AS1 (GJD3 antisense RNA 1)
Synonyms: UPLA1
Gene: Long non-coding RNA gene on chromosome 17 (40,360,655 to 40,365,372, forward strand). Ensembl gene ENSG00000266208.
Diseases named in the same sentence as GJD3-AS1 in open-access papers:
GJD3-AS1 is named in the same sentence as 4 diseases in open-access papers, as found by Europe PMC text mining. Sharing a sentence is not in itself a finding about the gene and the disease.
GJD3-AS1 shares sentences with these, for which no sentence is quoted: lung adenocarcinoma (2 papers); lung carcinoma (2); tumor (2); lymph node metastasis (1).